IL4 (interleukin 4)
Diseases named in the same sentence as IL4 in open-access papers (continued):
Sharing a sentence is not in itself a finding about the gene and the disease.
colorectal cancer (56 papers, 2008 to 2025). A primary or metastatic malignant neoplasm that affects the colon or rectum. "Through the use of MR analysis, our study revealed an inverse association between IL-4, and IL-13-regulated eosinophils and the risk of colorectal cancer in both cohorts." (PMID 39181688, 2024). "The IVW method was employed to examine the association between eosinophils regulated by gene IL-4, IL-5, IL-13, IL-4R, and IL-5RA and the risk of colorectal cancer and skin malignancies." (PMID 39181688, 2024). "In bone metastasis of colorectal cancer, IL-4 promoted the proliferation of early OCPs by binding its receptor IL-4α, while IL-4 deficiency impaired bone resorption." (PMID 36077242, 2022). "In previous studies, IL-4 and IL-4 signaling genes play crucial roles and associate with the progression of colorectal cancer." (PMID 33506057, 2021). "Recently, IL-4 and IL-13 and their receptors (IL-4R and IL-13R) have been shown to be increased in colorectal cancer tissues, and this elevation was also shown to be associated with local metastasis." (PMID 32931721, 2020). "In an additional study of an autologous approach using tumor samples and peripheral blood mononuclear cells from patients with colorectal cancer, the blockade of IL-4 was associated with an increased efficiency of tumor-specific T cell reactivity." (PMID 33255425, 2020). "Similar results were observed in a case-control study conducted in Spain in which individuals carrying the IL4 rs2243250 variant allele had a significantly increased risk of colorectal cancer when consuming a pro-inflammatory diet." (PMID 28051997, 2017). "The utilization of drugs targeting IL-4, and IL-13, which regulate eosinophils, may potentially elevate the risk of colorectal cancer." (PMID 39181688, 2024). "Consequently, it is plausible that drugs targeting IL-4, and IL-13 may elevate the risk of developing colorectal cancer." (PMID 39181688, 2024). "In colorectal cancer, IL-4 plays context-dependent roles in both tumor promotion and tumor suppression." (PMID 40622490, 2025). "IL-4 is overexpressed during the initial stages of colorectal cancer (CRC) development, such as in hyperplastic polyps, adenomas, and serrated adenomas." (PMID 41239618, 2025). "Lupeol presence was previously reported to affect IL4, known to promote colorectal cancer progression, which underscores the extract's impact on apoptosis induction and tumor suppression." (PMID 40672135, 2025). "Studies have shown that IL-4 mediates tumor cell proliferation and metastasis in gastric and colorectal cancers." (PMID 40040692, 2025). "The plasma levels of several cytokines (interleukin-1β /IL-1β/, IL-2, IL-4, IL-10, IL-12, IL-15, TGFβ and IFNγ) of 20 patients with colorectal cancer and 21 healthy individuals were determined by ELISA." (PMID 39456247, 2024). "A recent study revealed ILC2s to be the major source of IL-4 and IL-13 in tumours in a mouse model of colorectal cancer (CRC), and that ILC2-derived IL-4 and IL-13 promote M-MDSC expression both in vitro and in vivo." (PMID 38464388, 2024). "Many studies demonstrated that IL-4 as an autocrine growth factor enhances tumor cell survival, apoptosis resistance and growth in thyroid cancer, pancreatic cancer, colorectal cancer and prostate cancer 37-40." (PMID 38773979, 2024). "Colorectal cancer-related cancer-initiating cells evade immune surveillance through IL4/IL4R-mediated inhibition of T cell proliferation." (PMID 33419470, 2021). "The bulk of existing studies on claudin-2 in the gastrointestinal tract concerns colorectal cancer, where it is upregulated in response to IL-4 and IL-13 and involved in promoting proliferation, survival, migration, colony formation, and drug resistance." (PMID 32630408, 2020).
colorectal cancer (continued). "A growing body of evidence supports a role for the TH2-cytokines IL-4 and IL-13 in the pathogenesis of pre-malignant chronic inflammatory diseases of the gastrointestinal tract and in the enhancement of colorectal cancer cell proliferation." (PMID 28498822, 2017). "It should also be pointed out that some previous studies have reported that IL-4 is growth inhibitory for certain colorectal cancer cells, including the HT-29 cell line, while stimulating tumor cell proliferation in other tumor cell types." (PMID 28498822, 2017). "Th2 response, resulting in IL-4 production, was reported to be enhanced in the peripheral blood of patients with bladder and colorectal cancer compared with healthy controls." (PMID 21698244, 2011). "In the present study, we compared the frequency of a series of polymorphisms in different inflammatory response genes associated with IBD (DLG5, IL-4, OCTN, TNFα and NOD2) in colorectal cancer cases against controls." (PMID 18433468, 2008). "IL-4, IL-5, and IL-13 are overexpressed in colorectal cancer (CRC)." (PMID 41155334, 2025). "Similarly, in CRS-induced colorectal cancer mice, increased 5-HT levels are accompanied by reduced Th2 cells and lower IL-4 levels." (PMID 39247815, 2024). "The analysis revealed a negative correlation between eosinophils regulated by IL-4, and IL-13 and the risk of colorectal cancer (P < 0.05)." (PMID 39181688, 2024). "The analysis revealed a negative correlation between eosinophils regulated by IL-4, IL-5, and IL-13 and the risk of colorectal cancer (P < 0.05)." (PMID 39181688, 2024). "Significantly elevated levels of IL-4, IL-8 and IL-9 were observed in colorectal cancer." (PMID 37007080, 2023). "When we examined pro-tumoral cytokines, such as IL-2 and IL-4, we found that a high colorectal cancer PRS was associated with high IL2 score 21,050,467 (1.09; 1.004–1.18; p = 0.0434) and IL-4 score 21,050,467 (1.12; 1.03–1.21; p = 0.0116) levels in the early stages." (PMID 36428664, 2022). "MiR-195-5p was reported to inhibit NOTCH2 expression and activation in a post-transcriptional manner, leading to the down-regulation of NOTCH2/GATA3-mediated IL-4 secretion in colorectal cancer cells, ultimately suppressing M2-like TAM polarization and tumor progression." (PMID 35996149, 2022). "Recently, we found that IL-4 secreted by colorectal cancer cells affected M2 polarization of TAM." (PMID 32228612, 2020). "Furthermore, recent studies have demonstrated that IL-4 and IL-13, as well as the Type II receptor they share, are expressed widely in human colorectal cancers, as well as in a variety of other epithelial malignancies." (PMID 28498822, 2017). "In contrast, IL-4 aids cancer-initiating cells (CICs) responsible for tumor initiation, propagation, and resistance to chemotherapy, to escape from T cell-mediated immunosurveillance through membrane-bound IL-4 in colorectal cancer patients." (PMID 25590298, 2015). "Ten SNPs in the following six genes: NOD2 (2140 C/T, 2722 G/C), DLG5 (113 G/A), OCTN1 (1672 C/T), OCTN2 (-207 G/C), IL4 (-590 C/T) and TNFα (-308 G/A, -857 C/T, -863 C/A, -1031 T/C) were screened in a consecutive series of colorectal cancer patients using a two-staged approach." (PMID 18433468, 2008). "Colorectal cancer cells were cultivated using three different conditions: naive macrophages-conditioned medium (M0-CM), M0 macrophages treated with IL-4-conditioned medium (IL-4-CM), and M0 macrophages treated with both IL-4 and 23-HBA-conditioned medium (IL-4+23-HBA-CM)." (PMID 38554148, 2024). "For example, in colorectal cancer, NOTCH2 expression was shown to enhance GATA3-mediated IL-4 secretion, directly promoting M2-type TAM polarization." (PMID 41200204, 2025). "Activation of the Extracellular signal-regulated kinase (ERK) pathway via IL4/IL4R signaling plays a critical role in the proliferative phase of preosteoclasts, contributing to colorectal cancer bone metastasis." (PMID 40656893, 2025).
colorectal cancer (continued). "miR-195-5p inhibits IL-4-mediated M2 macrophage polarization by binding to the IL-4 3′-UTR, impairing the epithelial-mesenchymal transition (EMT) in colorectal cancer cells, thereby reducing Notch2 expression." (PMID 36362044, 2022). "IL-4 induced STAT6 signaling in promoting cell proliferation/growth and cell apoptosis resistance and induced epithelial-mesenchymal transition (EMT) in colorectal cancer cells via E2F1/SP3/STAT6 axis." (PMID 33506057, 2021). "In line with this phenomenon, previous studies have shown that patients with bladder and colorectal cancer have decreased proportions of IFN-γ/IL-2-producing Th1 cells, while increased proportions of IL-4/IL-10-producing Th2 cells, in peripheral blood." (PMID 29849497, 2018). "The presence of a Th2 gene signature, which includes IL-4, IL-5, and IL-13, in human colorectal cancer does not appear to have prognostic significance." (PMID 41239618, 2025). "Interestingly, the percentage of Tregs and IL-4-producing cells in EGPA patients was higher than in healthy mucosa, similarly to that detected in colorectal cancer." (PMID 35740247, 2022). "IL-4 autocrine response mediated colorectal cancer stem-like cell (CSC) survival and chemotherapeutic resistance through protecting the tumorigenic CD133+ CSC apoptosis; blocking or inhibiting IL-4 signaling sensitizes CSCs to apoptosis and increases the efficacy of cytotoxic therapy in vivo." (PMID 33506057, 2021).
Anxiety (51 papers, 2006 to 2026). Intense feelings of nervousness, tension, or panic often arise in response to interpersonal stresses. "Anxiety has also been associated with lower levels of anti-inflammatory cytokines such as IL-4 and IL-10." (PMID 41462928, 2025). "Our findings that deficient neurogenesis and anxiety‐like behaviours following microglial Arid1a deletion was rescued by Il4 stimulation in vivo opened a new avenue of mitigating depressive illness through manipulation of microglial polarization states." (PMID 35854653, 2022). "Deficiency in meningeal-derived cytokines, such as IL-4, IL-13, and IL-17α, has been shown to impaired learning, memory, social, and anxiety-like behaviors." (PMID 36703978, 2022). "We here demonstrate that IL-4 is present within the brain parenchyma and that IL-4Rα deficiency leads to reduced anxiety levels with impaired fear stimulus learning and exploratory drive while general learning is not affected." (PMID 35587822, 2022). "Understanding the interplay between trypanosome infections, neuroinflammation, and IL-4 signalling pathways is crucial for developing therapeutic strategies aimed at mitigating anxiety and other neuropsychiatric manifestations associated with parasitic infections." (PMID 40977748, 2025). "We found that IL-4 and IL-12 were significantly associated with anxiety." (PMID 36405903, 2022). "Second, in the HA rats, liver damage and anxiety were associated with an imbalance between GCs and cytokines that expressed in the decrease of blood Cort with a simultaneous increase of IL-1 and IL-2 and with a decrease of IL-4 and IL-10 concentrations in the blood and in the liver." (PMID 37629192, 2023). "Research indicates that blocking IL-4Rα prevents the anxiolytic effects of certain treatments, highlighting the importance of IL-4 signalling in regulating anxiety." (PMID 40977748, 2025). "For instance, IL-4 knockout mice, which lack this anti-inflammatory cytokine, display increased anxiety-like behaviours, suggesting that IL-4 plays a protective role against anxiety." (PMID 40977748, 2025). "It has been reported by Linda Witek‐Janusek and colleagues that having the breast biopsied for cancer diagnosis is an emotional experience marked by increased perceived stress, anxiety, and mood disturbances with the increase in IL‐4 production." (PMID 36965094, 2023). "Some of these cytokines performed fundamental functions in CNS: IL-1β in learning and synapse formation, IL-4 in neurogenesis and spatial learning, IL-17A in synaptic plasticity and in the management of anxiety." (PMID 37588589, 2023). "Our result also supports the finding that IL-4 knock-out mice display anxiety-like behavior, in comparison to wild-type mice." (PMID 36405903, 2022). "Among the cytokines involved in the pathophysiology of anxiety, IL-4 stands out for its anti-inflammatory activity." (PMID 36035219, 2022). "For instance, significantly lower levels of stimulated IL-4 and IL-10 were witnessed in high-anxiety students measured one day before an academic examination, while a videotaped speech task stressor did not affect IL-4 levels." (PMID 31226144, 2019). "It was observed that IMO stressed rats had significantly increased anxiety and reduced IL-4 protein level in the brain." (PMID 26903707, 2016). "We also focused on the correlation of IL-4 secretion, anxiety-like behavior, and HPA-/SAM-axes activation in the stress response." (PMID 26903707, 2016). "However, the authors reported that in AD patients withdepressive symptoms and state anxiety, natural killer (NK) activity was reduced along withplasma IL-4 levels." (PMID 34819201, 2021). "Exposure to 6 weeks of repeated injection resulted in an anxiety-like phenotype, decreased systemic inflammation (i.e., reduced plasma levels of TNFα and IL4), increased corticosterone reactivity, increased microglial activation and decreased neuronal differentiation in the dentate gyrus (DG)." (PMID 32958745, 2020).
Anxiety (continued). "In conclusion, stress-induced decline of IL-4 concentration from LC neurons may be related to anxiety-like behavior and an inverse relationship exists between IL-4 secretion and HPA/SAM-axes activation." (PMID 26903707, 2016). "Accordingly, it was concluded that stress-induced decline of IL-4 concentration from LC neurons may be related to anxiety-like behavior and an inverse relationship exists between IL-4 secretion and HPA/SAM-axes activation." (PMID 26903707, 2016). "In addition, IL-4 was found to be correlated with severity of anxiety in subjects affected by AD." (PMID 37781860, 2024). "A reduction in depressive and anxiety symptoms (measured with HADS) was presented in two randomized placebo-controlled studies on dupilumab (a monoclonal antibody binding to IL-4/IL-13 receptors), which may link inflammation and mood disorders in the AD patient population." (PMID 37685808, 2023). "In experimental models of stress, the decline in IL-4 levels in the locus coeruleus may be involved in anxiety-like behavior and an inverse relationship between IL-4 secretion and hypothalamic-pituitary-adrenal (HPA)/sympathetic-adrenal-medullary-axes activation has been reported." (PMID 35782423, 2022). "The differences in gene expression between HiAnx and LoAnx mice described in this section were based on anxiety phenotype determined by the LDA, except for differences in IL-4 gene expression which were based on anxiety phenotype determined by the EPM." (PMID 22558071, 2012). "Participants with anxiety in this study showed higher eotaxin (pro-inflammatory chemokine) and higher IL-4 (anti-inflammatory cytokine) concentrations in blood plasma than participants without anxiety." (PMID 39514787, 2024). "In our study, IL-4 was negatively correlated with anxiety in patients with non-acral melanoma, TNM stages II to IV, and non-acral melanoma with TNM stages II to IV." (PMID 36405903, 2022). "For the total study population, HADS anxiety scores showed a negative correlation with IL-4 and IL-6 (p ​= ​.021, ρ ​= ​−0.184; and p ​= ​.023, ρ ​= ​−0.182)." (PMID 34589849, 2020). "Since overall biological function is ultimately influenced by relative proportions of counteracting factors, we also examined the effects of anxiety phenotype on the ratios of protective versus harmful chemokines (CTACK/CCL22) and cytokines ((IL-12+IFN-γ)/(IL-10 + IL-4))." (PMID 22558071, 2012).
co-infection (51 papers, 2008 to 2026). "We previously reported that this co-infection is facilitated by S. haematobium eggs triggering interleukin-4 (IL-4) production and sought to dissect the underlying mechanisms." (PMID 33298153, 2020). "Co-infection of T. gondii-infected mice with H. polygyrus was associated with a significant increase of the Th1-type response, whereas the IL-4 associated Th2 response was comparably suppressed in the brains of co-infected mice." (PMID 31352901, 2019). "And IL6 > 388.9 pg/mL and IL4>0.535pg/mL were independent risk factors for co-infection." (PMID 40416960, 2025). "Moreover, SL3261 co-infection led to loss of the M(IL-4) activation phenotype in NeMΦ, as measured by intracellular Relm-α expression, but induction of NOS2 was independent of previous M(IL-4) activation as indicated by equivalent expression in Relm-α positive and negative cells." (PMID 28334040, 2017). "M(IL-4) resulted in increased IL-4 when infected with only the G strain and reduced IL-10 during co-infection." (PMID 36389843, 2022). "The described co-infection method with IL-4 and PDGF-BB lentiviral vectors was used to generate the genetically modified MSCs populations." (PMID 33413614, 2021). "mansoni coinfection had increased IL-4 and expanded CD8+ T-cell viral-specific effector responses in the lung, leading to enhanced control of the respiratory virus." (PMID 34015063, 2021). "On the contrary, the secretion of Th2 cytokine IL-4 was significantly inhibited by co-infection of T. gondii." (PMID 32295161, 2020). "In this co-infection model peak expansion and accumulation of H. polygyrus driven M(IL-4) occurs before bacterial challenge." (PMID 28334040, 2017). "Our data show that IL-4-expressing Th2 cells, serum IgE, and functional parasite expulsion are reduced during co-infection." (PMID 26147567, 2015). "This is in line with previous reports, including reduced schistosome-specific IL-4 and IL-5 in Plasmodium and schistosome co-infected individuals and suppressed IL-4 responses during H. polygyrus and Plasmodium yeolii co-infection." (PMID 26147567, 2015). "Unexpectedly, EF IgG1 and IgE switching in the spleen was detectable at similar levels in both co-infected and Nb-only infected mice, despite reduced levels of IL-4 after co-infection." (PMID 25474738, 2014). "In contrast, levels of IL-4 and IL-13 were greatly reduced at times after co-infection compared with Nb-only infected mice." (PMID 25474738, 2014). "Our results verify reports illustrating that M. bovis co-infection increase helminth parasite burden and correlates with decreased IL-4 and IL-13 cytokine production." (PMID 24433309, 2014). "Co-infection group has lower IL-4 concentration compared with both HIV mono- and HCV mono-infection group, while higher than healthy control group." (PMID 22533731, 2012). "In this study, dectin-1 is highly expressed in the lesions of the rats of the co-infection group and is Th2 independent as IL-4 is undetectable." (PMID 23285072, 2012). "In summary, co-infection of two avirulent HSV-1 in which one of the two viruses expressing IL-4 generated recombinant viruses in vivo." (PMID 21139679, 2010). "In young sexually active adolescent women diagnosed with co-infection of oncogenic human papillomavirus and CT, IL-4 transcripts correlating to IL-10 have been detected in cervical samples." (PMID 19698128, 2009). "We also found higher level of IL4 in patients with co-infections." (PMID 40416960, 2025). "Moreover, patients have extreme elevations of HHV-8 viral load and IL-6 level; it has been reported that in HIV/HHV-8 coinfection, IL-4, IL-6, and IL-10 levels are increased." (PMID 35053573, 2022). "Excluding co-infection with soil-transmitted helminths, individuals with C. sinensis still had significantly higher antigen-specific IgG and IgE levels, and diminished serum levels of IL-1β, IL-2, IL-4, IL-12p70, IL-17A, IFN-γ and TNF-α." (PMID 36083861, 2022).